BCL2 (BCL2 apoptosis regulator)
Diseases named in the same sentence as BCL2 in open-access papers (continued):
Sharing a sentence is not in itself a finding about the gene and the disease.
tumor (continued). "In contrast, RTA 405 increased the levels of NRF2, but not IKKβ or BCL2, in human tumor cell lines." (PMID 26301506, 2015). "We observed that TQ inhibited tumor cell growth in vitro, where treatment with TQ arrested the cell cycle in G1 by upregulating p21 and downregulating cyclinD1 and CDK2 expression; moreover, TQ induced apoptosis by decreasing expression of Bcl-2 and increasing expression of Bax." (PMID 26416455, 2015). "The observed tumor growth inhibition after treatment with imatinib and vitamin D analogs, PRI-2191 and PRI-2205, could be the result of apoptotic cell death, since downregulation of anti-apoptotic Bcl-2 protein was observed." (PMID 26580599, 2015). "Pathologic response in the vitD cohort was significantly associated with HR negative (OR, 0.26; 95% CI, 0.15–0.47), moderate or high tumor grade (OR, 9.64; 95% CI, 1.26–73.93), low levels of Bcl2 (OR, 0.41; 95% CI, 0.22–0.79), and Ki67 >10 (OR, 2.46; 95% CI, 1.13–5.31)." (PMID 24719175, 2014). "However, PM-induced downregulation of Bcl-2 was not mediated through the proteolytic degradation, since treatment of tumor cells with PM in the presence of proteasomal and calpain inhibitors failed to prevent downregulation of Bcl-2." (PMID 24603988, 2014). "Owing to their imbalance expression levels in tumor cells and their capability to regulate MOMP, Bcl-2 proteins have been viewed as promising therapeutic targets in cancer and research efforts have lately been focusing on the development of drugs targeting Bcl-2 proteins." (PMID 24603326, 2014). "However, the BH3-only proteins induced by ERK inhibition may prime tumour cells for apoptosis, thus providing a rationale for combining an ERK or MEK inhibitor with BCL2-inhibitors." (PMID 26556430, 2014). "Furthermore, two other reports suggest that Bcl-2 expression is not related to tumor progression nor the prognosis in ESCC." (PMID 25438156, 2014). "The balance of Bcl-2/Mcl-1 proteins has also been largely shown to impact the efficacy of ABT-737, suggesting that modulation of Noxa and Mcl-1 could be used as a strategy for sensitizing tumor cells to ABT-737." (PMID 24454684, 2014). "The tumor was negative with Bcl-2, desmin, HMB-45, S100, FVIII, and CD31." (PMID 23662242, 2013). "Some of the miRNAs with recently identified targets in vitro in various tumor settings other than GIST include: miR-132 targeting Rb1, miR-193b targeting CCND1 and Mcl-1, miR-455-3p targeting Smad2, miR-125b targeting Mcl-1 and Bcl-2 and miR-542-5p targeting survivin." (PMID 23717541, 2013). "Moreover, the anti-tumor effects of miR-195 in TSCC may be partially mediated by its inhibition of Cyclin D1 and Bcl-2 expression." (PMID 23451060, 2013). "Some researchers have argued that there may be a correlation between PAL and Epstein–Barr virus infection, while others have reported that tumor cells of primary adrenal DLBCL usually express BCL-2 with a non-germinal center B-cell phenotype." (PMID 23915571, 2013). "In the PC-3 tumor xenograft model, AMD3100 significantly inhibited tumor growth, while AMD3100-treated PC-3 tumors had lower levels of microvessel formation and a lower immunoreactivity for the proliferation marker Ki-67 and the anti-apoptotic marker Bcl-2 compared to control tumors in vivo." (PMID 24137439, 2013). "Notably, Bcl-2 acts as a signaling molecule by activating the NF-kB signaling pathway and inducing expression of CXCL1 and CXCL8 that in turn enhance the invasive phenotype of neighboring tumor cells." (PMID 24391922, 2013). "In addition, inhibition of apoptosis via the Bcl-2 pathway, and the down-regulation of PMS2 and topoisomerase 11 DNA mismatch repair proteins have been proposed as mechanisms that desensitize tumor cells in spheroids to antitumor agents." (PMID 24146752, 2013). "In addition, TIM-3 was co-expressed with Bcl-2 and PCNA, indicating that TIM-3 may regulate tumor cell apoptosis and proliferation." (PMID 24137353, 2013).
tumor (continued). "Another complicating factor in tumor cells may be a non-functional apoptotic pathway, especially when Bcl2 is overexpressed and there is resistance to apoptosis or alternative survival pathways." (PMID 22680924, 2012). "Secondly, the relationship between tumor recurrence and bcl-2 was not investigated." (PMID 22216342, 2011). "Thus, 2DG appears to sensitize tumor cells to Bcl-2 antagonists through mechanisms that do not depend on glucose-depletion or ER stress." (PMID 21949692, 2011). "Systemic administration of G3139 to Shionogi tumor-bearing mice led to a rapid decrease of tumor size (higher when chemotherapy was simultaneously administered), whereas the oligonucleotide did not affect Bcl-2 expression in normal organs." (PMID 24212662, 2011). "We could not observe any correlation between bcl-2 expression in the tumor and prognostic variables or PSA recurrence." (PMID 20877598, 2010). "After confirming the Stat-5-mediated pathway as the major pathway in tumor-induced CD4+ T cell apoptosis, we undertook two different approaches to identify the isoform(s) of Stat-5 involved since both Stat-5A and Stat-5B isoforms play critical role in Bcl-2 induction in T cells." (PMID 19812686, 2009). "Messenger RNA levels of Bax and of the antiapoptotic Bcl-xL and Bcl-2 (data not shown) did not change dramatically among all tumours tested, whereas Mcl-1 mRNA expression showed a small yet significant increase, but at a much lower level than the BH3-only Puma, Noxa and Bim-EL." (PMID 19455143, 2009). "The correlation between BCL-2 expression, tumor size and mitotic rate was not significant." (PMID 18651966, 2008). "Thus, high BCL2 levels and/or high FOS levels may only reflect aggressiveness of the disease or may be indicative of an intact pathway that is driving tumor growth and that should be sensitive to endocrine therapy." (PMID 18928543, 2008). "Furthermore, a significant correlation of tumour location and Bcl-2 expression or the MSI phenotype was found with left-sided tumours revealing higher Bcl-2 expression levels (P=0.03) or with right-sided neoplasms showing an association with MSI+ cases (P<0.0001)." (PMID 17426704, 2007). "Also, this study suggests that in the absence of the tumor stage as a variable, Bcl-2 expression is a strong prognostic molecular marker of CRC." (PMID 19455238, 2007). "Bcl-2 expression was not related to the T stage or the tumour grade." (PMID 17031406, 2006). "We hypothesised that Bcl-2-negative tumour cells with higher proliferative activity, as demonstrated by Ki-67, may overcome the apoptotic effect of immune cells in this case." (PMID 17031406, 2006). "It is feasible that Bcl-2 represses immunotherapy-induced apoptosis in RCC cells, as all primary tumours from responders to immunotherapy were negative for Bcl-2 in this study; however, a clinical response was observed in only eight of 27 (29.6%) Bcl-2-negative cases." (PMID 17031406, 2006).
tumor (continued). "In contrast, Bcl-2-negative tumours are sensitive to immunotherapy-triggered apoptosis." (PMID 17031406, 2006). "Although only four of 101 specimens were caspase-3 positive, this might suggest caspase-3 involvement in apoptosis of tumour cells without Bcl-2 expression." (PMID 14710230, 2004). "It has also been observed that the tumor-suppressor PTEN, the Akt/PKB pathway inhibitor, was down-regulated drastically, leading to an increased activity of Akt/PKB, as shown by the anti-apoptotic protein Bcl-2 and the cell-cycle inhibitor p27kip, which were induced and inhibited, respectively." (PMID 15566568, 2004). "In other tumours bcl-2 positivity has not been clearly correlated with tumour aggressiveness." (PMID 12085183, 2002). "Bcl-2 staining was not related to histological grade of tumours." (PMID 12085183, 2002). "Bcl-2 staining intensity did not appear to have any significant relationship to the other clinicopathological variables; in particular it did not seem to be related to tumour grade (Fisher's Exact P=0.443)." (PMID 12085183, 2002). "Bcl-2-negative lesions were more frequent among patients who reached an objective clinical response, which is in agreement with previously reported data regarding other tumour types." (PMID 11237386, 2001). "Sixty-three (25%) tumours were scored bcl-2 negative and 188 (75%) tumours were bcl-2 positive." (PMID 7640218, 1995). "However, monotherapy with Bcl-2 inhibitors may not be sufficient, and combination strategies are often necessary to enhance tumor cell apoptosis and improve treatment response." (PMID 40841912, 2025). "In addition, protein expression of PCNA, CyclinD1, Bcl-2, Integrin α2/β1, p-FAK, p-PI3K (p85), p-AKT, p-mTOR, C-myc proteins were also significantly increased in the DLD-1 xenograft tumor treated with S. moorei and were reversed by RGD peptides in S. moorei-treated DLD-1 xenograft tumor." (PMID 39990665, 2025). "However, we observed that BCL-2 upregulation or downregulation in macrophages or tumor cells did not impact the polarization of M2-like macrophages to the M1-like phenotype, indicating that APG-2575 induces macrophage polarization in a BCL-2-independent manner." (PMID 38062129, 2024). "For example, activation of NF-κB/Bcl-2/Snail pathway increases chemotherapy resistance in NSCLC, and thus targeted drug delivery of this pathway would behave with good specificity and pharmacokinetic characteristics which could inhibit tumor cell proliferation." (PMID 37744063, 2023). "In this context, other BH3 mimetics such as ABT-737 and its oral derivative navitoclax, which bind to Bcl-2, Bcl-xL and Bcl-w (but not Mcl-1) with high affinity have also been investigated in MM, but their development was precluded either due to lack of anti-tumor activity or unacceptable toxicity." (PMID 36672426, 2023). "In addition to the tumor cell-autonomous Bcl-2-dependent resistance to Regorafenib, we identified a non-autonomous mechanism dependent on infiltrating macrophages that involves the COX2-PGE2 signaling reducing the susceptibility to regorafenib and promotes further tumor growth." (PMID 37620408, 2023). "Two small-molecule Bcl-2 inhibitors, HA14-1 and ABT-737, were found to improve the in vitro cytotoxicity of CTLs and NK cells to the lymphoma and melanoma cells, which might be attributed to sensitizing tumor cells to perforin and granzyme-B with drug treatments." (PMID 36080223, 2022).
tumor (continued). "Moreover, DK1 also enhanced the expression of several other tumor suppressor genes that are related to this pathway such as FOXO, TP73, CDKN1A, Caspase, CYCS, and GADD45A while impeded the expression of other proto-oncogenes namely PIK3R3, BCL-2, IGFBP2, HGF, and FGF." (PMID 34204873, 2021). "In addition, reverse transcription polymerase chain reaction (RT-PCR) analysis of these tumor samples revealed that the MS67 treatment led to down-regulation of WDR5 target genes such as ribosome subunits and oncogenesis-related transcripts including BCL2 and CSNK1E." (PMID 34586829, 2021). "Thus, the sequential combination of the BCL-2 inhibitor Navitoclax could promote the death of tumor cells, so there was no doubt that adopting this treatment method was of positive significance." (PMID 34603598, 2021). "IL-17 could stimulate tumor proliferation and self-renewal and promote tumor infiltration and angiogenesis by activating downstream transcription factors (STAT, NF-κB, and AP1), antiapoptotic proteins (mTOR, Akt, Bcl-2, Erk, and Bax), and kinases (MAPK and HER1)." (PMID 34938816, 2021). "Interestingly, while BCL-2 was also highly expressed pre-CDA the level of this protein returned to healthy control ranges post-CDA (pre vs. healthy adj p = 3.05 × 10–5, pre vs. post adj p = 3.18 × 10–12), likely reflecting the change in tumour burden in these patients." (PMID 34561502, 2021). "Furthermore, AZD5991 induced tumour regression in the MV4-11 xenograft model of AML and exhibited a synergistic effect on tumour regression in the OCI-AML3 xenograft model of AML, when combined with the selective BCL-2 inhibitor venetoclax vs. venetoclax monotherapy." (PMID 34249942, 2021). "Besides other factors, the tumor size is also accountable due to the presence or absence of anti-apoptotic proteins; in particular, we observed that Bcl-2 expression was present in moderate or strong staining in tumors 2-times larger than in tumors with absent or low expression." (PMID 32466539, 2020). "A significant Bcl-2 down expression and a consequent increase in the Bax/Bcl-2 ratio in LAIR-1 overexpression tumor samples suggests that apoptosis via the regulation of the PI3K-AKT pathway and Bcl-2 family proteins may play an important role in the tumor suppressive function of LAIR-1 in vivo." (PMID 32628130, 2020). "Besides CD56, BPDCN may also express other antigens negative in normal pDCs, including BCL6, IRF4, and BCL2 (the latter potentially acting against tumour cell apoptosis)." (PMID 31035408, 2019). "Importantly, we observed that PPARγ activation in the tumor tissues was in line with the expression of the target gene PTEN, but inversely correlated with the activation of Akt, as indicated by the phosphorylation of Akt (Ser473) and its downstream FoxO1 (Ser256) and Bcl2 (Ser70)." (PMID 30845932, 2019). "If these results could be extrapolated to human T-cell tumors (and maybe also other tumor types), then an effective treatment regimen, if tolerated, could consist in simultaneous inhibition of AKT or TcR-signaling and inhibition of anti-apoptotic Bcl-2 proteins." (PMID 29765548, 2018). "Consequently, the ratio of Bcl-2/Bax is an essential factor to determine whether a tumor cell commits apoptosis or not." (PMID 30454003, 2018). "However, forced expression of BCL2 or CCND1 alone does not suffice for in vivo tumour formation." (PMID 30451834, 2018). "Efficacy, as measured by tumor growth inhibition (TGI) was assessed in 3 models of ABC (U2932, RIVA, and OCI-LY10) and two models of GCB (SU-DHL-4 and NU-DHL-1) subtype DLBCL to make an initial assessment of whether response to BCL-2/MCL-1 inhibition can be predicted based on genetic subtyping." (PMID 29269870, 2017).
tumor (continued). "In addition, APS inhibit the tumor cell growth in Kunming mice with Ehrlich's ascites carcinoma, decrease Bcl-2 and CDK4 levels, increase the percentage of CD3+ and CD4+ T-lymphocytes, the ratio of CD4+/CD8+ T cells and the expression of IL-2/IL-2R in spleen and Bax in tumor tissue." (PMID 29344421, 2017). "Furthermore, lncRNA ANRIL knockdown in tumour cells inhibited proliferation, induced apoptosis and increased cisplatin cytotoxicity of the tumour cells via impairment of the drug transporters MRP1 and ABCC2, which could be restored by treatment with human MK in a caspase-3/BCL-2-dependent manner." (PMID 29176691, 2017). "Interestingly, it was found that free G3139 triggered mild tumor suppression during the first two weeks of treatment, which could not be explained by its antisense mechanism since no corresponding Bcl-2 reduction was observed in free G3139-treated tumors." (PMID 27034925, 2016). "Furthermore, the decrease in PCNA protein level and the increase in cleaved-PARP protein level were observed in tumor tissue using Immunohistochemistry and Western blotting analyses, while the level of Bcl-2 protein did not change (**P < 0.01, ****P < 0.0001, vs control)." (PMID 26811493, 2016). "Interestingly, two tumor-suppressive miRNAs, let-7 and miR-34, are the most common altered miRNAs in NSCLC tumor tissue The reduction in let-7 and miR-34 expression is relevant in the NSCLC oncogenic phenotype and is involved in the maintenance of oncogene addiction, via RAS, BCL2, MET or MYC." (PMID 26425674, 2015). "Moreover, miR-503 has been widely described in the literature as an anti-tumor miRNA that regulates the expression of key cell cycle proteins, such as CDC25A and cyclins D1 and E1, as well as cell proliferation via E2F3 and PI3K regulation and the apoptosis status via BCL-2 inhibition." (PMID 25860935, 2015). "However, in many tumour cells, the PI3K/AKT pathway is highly active, which could in turn adversely affect the integrity of the mitochondria outer membrane by indirectly activating anti-apoptotic BCL-2 family proteins, such as BCL-2 or BCL-xL53." (PMID 26446703, 2015). "We did not observe a correlation between the expression of SRC-3, ErbB-2, hTERT, PTEN, FoxO1, Bcl-2, SMAD4, c-myc, Hsp70, Hsp90 and CHIP expression in BxPC-3 cells, this result could be explained by feedback of complicated signaling network in different tumor environments." (PMID 24722501, 2014). "Nevertheless, BCL2 activation is not sufficient to produce malignancy, since BCL2 activation has also been shown to be present in either circulating B cells in healthy individuals and in possible precursor lesions including intrafollicular neoplasia/in situ FL." (PMID 23028387, 2012). "However, lack of tumor Bcl-2 expression fails to confirm an in vivo mechanism of action." (PMID 21479172, 2011). "Indeed, tumor-shed PGE2 down-regulates IL2Rγc expression, reduces phosphorylation as well as activation of Janus kinase 3 (Jak-3)/signal transducer and activator of transcription 5 (Stat-5) and decreases Bcl-2/Bax ratio thereby leading to activation of intrinsic apoptotic pathway." (PMID 19812686, 2009).